STAT3 (signal transducer and activator of transcription 3)
Diseases named in the same sentence as STAT3 in open-access papers (continued):
Sharing a sentence is not in itself a finding about the gene and the disease.
colorectal cancer (continued). "Since BZA induces apoptosis in colorectal cancer via suppression of gp130/STAT3 inflammatory signalling, we assessed whether the combination of BZA and SMAC-mimetics could be beneficial for colorectal cancer treatment." (PMID 38600086, 2024). "Moreover, CCL5 has been reported to be involved in cancer metastasis and progression through the STAT3 signaling pathway in breast, bladder, and colorectal cancers." (PMID 39126553, 2024). "However, very little about the STAT3-dependent cellular mechanisms underpinning colorectal cancer progression is understood." (PMID 38600086, 2024). "Moreover, the overexpression of LOX in colorectal cancer cells triggers the production of interleukin-6 (IL-6), which in turn activates the signal transducer and activator of transcription 3 (STAT3) signalling pathway." (PMID 39247609, 2024). "STAT3 is also an important prognostic marker for colorectal cancer." (PMID 38710698, 2024). "TAMs have also been shown to promote invasion, migration, and metastasis in colorectal cancer via regulation of the JAK2/STAT3/miR‐506‐3p/FoxQ1 axis resulting in the production of CCL2 which in turn promotes the recruitment of more TAMs in a positive feedback loop." (PMID 38703051, 2024). "Moreover, the phase-III study of NP in resistant colorectal cancer highlighted Stat3 as a key target in patients with high pStat3 expression." (PMID 39356934, 2024). "This process may be associated with succinate activation of STAT3, which upregulates EMT-related expression and subsequently promotes distant metastasis in colorectal cancer." (PMID 38486162, 2024). "Additionally, Dp has also been shown to regulate the JAK2/STAT3 signaling pathway, inducing apoptosis in colorectal cancer cells." (PMID 39781272, 2024). "Interestingly, a recent study showed that miR-196-5p promoted stemness of colorectal cancer cells by activating STAT3 signaling pathway." (PMID 38509141, 2024). "STAT3 negatively regulates the expression of CHAC1 in colorectal cancer cells." (PMID 39534397, 2024). "Furthermore, in colorectal cancer, IL-6 produced by TAMs activates the STAT3 pathway and consequently blocks expression of the miR-204-5p tumor suppressor." (PMID 38280079, 2024). "In addition, STAT3 can promote epithelial-mesenchymal transition (EMT) in colorectal cancer, thus promoting cancer metastasis." (PMID 38486162, 2024). "Notably, the interleukin-6 (IL-6) family of cytokines, including IL-6, IL-11 and leukaemia inhibitory factor (LIF), directly activate STAT3 and contribute to the establishment and progression of colorectal cancer." (PMID 38600086, 2024). "We then wondered if HSP110 inhibition could also alter STAT6 signaling, since we previously showed that HSP110 has a role in STAT3 activation in colorectal cancer." (PMID 38773631, 2024). "The inhibition of glycolytic genes in colorectal cancer cells by diclofenac might be explained by a reduction in c-MYC expression that alters STAT-3 signalling through its decreased phosphorylation." (PMID 38229111, 2024). "Moreover, PDIA3 was demonstrated to catalyze colorectal cancer cell motility by governing the STAT3/PD-1 pathway, while simultaneously modulating M2 macrophage polarization and protease secretion." (PMID 38761176, 2024). "In colorectal cancer, for example, IL-6 signalling via STAT3 results in repression of a micro-RNA (miR-34a), that in turn results in increased expression of EMT signature genes associated with invasion and metastasis, such as vimentin, SNAIL, SLUG and ZEB1, with concommitant loss of E-cadherin." (PMID 38689325, 2024). "Cellular experimentation underpinned the proposition that PDIA3 impels the M2 polarization of tumor-aligned macrophages, alongside fostering proliferation and the potential for metastasis in colorectal cancer, all by the delicate modulation of the STAT3/PD-1 signaling continuum." (PMID 38761176, 2024).
colorectal cancer (continued). "By blocking the JAK2/STAT3 signaling pathway, ATL I also decreases the proliferation and causes apoptosis of human colorectal cancer cells HCT116 and SW480, slows glycolysis in CRC cells by reducing HK2 expression, and inhibits tumor growth in xenograft colorectal cancer mice." (PMID 37241729, 2023). "Besides MHME, it is noteworthy that we previously demonstrated that HME and DHME target the STAT3-mediated pro-survival signaling to slay bladder and colorectal cancer cells, respectively." (PMID 37893115, 2023). "Augmentation of CD4+ T cells, CD8+ T cells and CD49b+ NK cells, as well as increased expressions of IFNg, IL10, CXCR4, and reduced expressions of IL17, STAT3 screened from gene and protein levels, jointly create a microenvironment conducive to inhibit the progress of colorectal cancer." (PMID 37143538, 2023). "This hypothesis was consistent with literature data that PGRN was elevated in breast and colorectal cancer tissues and positively correlates with STAT3 activation." (PMID 37660003, 2023). "The study also discovered that Alistipes could promote the development of colorectal cancer through activation of the interleukin-6/signal transducer and activator of transcription 3 signaling pathway." (PMID 38033576, 2023). "Whether the dysregulation of the JAK1/STAT3 pathway can directly shape the characteristics of colorectal cancer cells?" (PMID 38001065, 2023). "Besides, online data mining revealed the expressions of NF-κB and STAT3 were positively correlated in clinicopathological colorectal cancer samples, which provided new evidence for the role of NF-κB in regulating STAT3 expression." (PMID 38001065, 2023). "In colorectal cancer cells, STAT3 can directly target the promoter of cyclin D1." (PMID 37701157, 2023). "Collectively, our results revealed that METTL3 simultaneously upregulated JAK1 and STAT3 expression in m6A-dependent and -independent manners, which contributed to STAT3 signaling activation, resulting in colorectal cancer proliferation and progression in vitro and in vivo." (PMID 38001065, 2023). "Moreover, the proliferation of HCT-116 and SW480 colorectal cancer cells decreased after STAT3 silencing." (PMID 38067351, 2023). "C. albicans mediates the up-regulation of macrophage glycolytic pathway, and up-regulates the expression and secretion of IL-7, and then induces type 3 intrinsic lymphocytes (ILC3) to express high levels of IL-22 through AhR and STAT3 pathways, which aggravates the progression of colorectal cancer." (PMID 37333850, 2023). "In colorectal cancer, STAT3 siRNA significantly decreases miR-4508 levels." (PMID 37781522, 2023). "The activation of STAT3 by IL-6/IL-11 in fibroblasts promotes the development of colorectal cancer." (PMID 38054820, 2023). "Besides, the active form of Rac1 promotes invasion of colorectal cancer cells through activation of STAT3 pathway." (PMID 37752569, 2023). "For example, it has been demonstrated that IL-22 acts on colorectal cancer cells to promote the activation of transcription factor STAT3 and expression of histone H3 lysine 79 methyltransferase, consequently increasing cancer stemness and tumorigenic potential." (PMID 38098005, 2023). "Furthermore, a study by Luo and colleagues in 2021 demonstrated that EGCG had an anti-proliferative effect on SW480, SW620, and LS411N colorectal cancer cells by down-regulating the level of STAT3." (PMID 35204178, 2022). "CAFs within the TME actively contribute to sustained STAT3 activation in colorectal cancer." (PMID 36016615, 2022). "Nevertheless, others have reported that supplementation of VSL3# with anti-inflammatory drug balsalazide in mice with colorectal cancer induced by azoxymethane/dextran sodium sulfate reduces tumor burden in association with increasing Bax/Bcl-2 ratio and lowers IL6/STAT-3 signaling." (PMID 35625485, 2022).
colorectal cancer (continued). "The results suggested that STAT3 might be an important target for the treatment of patients with colorectal cancer who have increased phospho-STAT3 expression." (PMID 35267638, 2022). "Previous studies have shown that LH2 could activate the STAT3 signaling to upregulate the HK2 expression in the colorectal cancer cells, thus mediating glycolysis." (PMID 35559258, 2022). "STAT3 also increases the survival of EGFR+ cancer stem cells in colorectal cancer." (PMID 35681787, 2022). "CD276 impacts colorectal cancer cell migration through the Jak2/Stat3/MMP-9 signaling pathway." (PMID 35296518, 2022). "Moreover, in ovarian, gastric, and colorectal cancers, it has been shown that downregulation of p-STAT3 activity increases autophagy of these tumor cells, and the occurrence and progression of these tumors are also suppressed." (PMID 35559037, 2022). "Interestingly, VCP promotes the growth, invasion, and metastasis of colorectal cancer through activation of STAT3 signaling." (PMID 35841038, 2022). "Recent studies have shown that inhibition of the activation of STAT3 could sensitize the effect of 5-FU by down-regulating cyclin D1 in colorectal cancer cells." (PMID 36157053, 2022). "RNF6 amplification could activate the JAK/STAT3 or Wnt/β-catenin pathway and serve as an unfavorable prognostic marker in colorectal cancer." (PMID 35568845, 2022). "However, in contrast to a previous report, a study demonstrated that only STAT1 and STAT3 were activated by IL-35 expressed by tumor-infiltrating Tregs in colorectal cancer during the induction of iTr35 cells." (PMID 35420296, 2022). "However, IL-22 can enhance STAT3 signaling in epithelial cells, increase proliferation, and play a role in colorectal cancer development." (PMID 35410210, 2022). "The aberrant activation of STAT3 is associated with the etiology and progression in a variety of malignant epithelial-derived tumors, including head and neck squamous cell carcinoma (HNSCC) and colorectal cancer (CRC)." (PMID 36509291, 2022). "NOVA1 enhanced IL-6/JAK2/STAT3 signaling in turn to up-regulate MMPs in colorectal cancer." (PMID 36284263, 2022). "STAT3 is translocated to the cell nucleus and induces IL-10 gene expression but also regulates proliferation, apoptosis, invasion, metastasis, and angiogenesis in colorectal cancer (CRC)." (PMID 35723375, 2022). "Moreover, the TNF-stimulated phosphorylation of ERK, p38, AKT, and STAT3 was decreased in both colorectal cancer cell lines." (PMID 35222445, 2022). "STAT3 (signal transducer and activator of transcription 3) is key in regulating the anti-tumor immune response and a therapeutic target of immune therapies in different cancer subtypes such as celecoxib in colorectal cancer and pyrimethamine in chronic lymphocytic leukemia." (PMID 35106465, 2022). "Moreover, trichostatin A (TSA) leads to the hyperacetylation of histones associated with SOCS1 and SOCS3 promoters, which significantly downregulates JAK2/STAT3 signaling in colorectal cancer cells." (PMID 35611249, 2022). "The role of IL-6 and STAT3 in promoting colorectal cancer has previously been reported." (PMID 35205671, 2022). "In the colorectal cancer, STAT3 is suppressed by miR-124-3p." (PMID 36295083, 2022). "It was observed that several important cancer-associated signaling pathways, including the Wnt signaling pathway, colorectal cancer metastasis signaling, etc., were activated, and the STAT3 pathway, ferroptosis, etc., were significantly suppressed between 5FUR CRC and parental cells." (PMID 35267590, 2022). "There is increasing evidence that some phytochemicals could be potential candidates for the treatment and prevention of colorectal cancer, in part by suppressing the activation of the STAT3 pathway." (PMID 35056682, 2022). "Inhibition of the STAT3 signaling pathway in cancer cells has been shown to result in inhibition of growth and induction of apoptosis, making it an attractive therapeutic target for colorectal carcinoma." (PMID 35056682, 2022).
colorectal cancer (continued). "In addition, both STAT3 and phosphorylated STAT3 (p-STAT3) were downregulated significantly by EGCG in three selected colorectal-cancer cell lines." (PMID 33747527, 2021). "Notably, miR-214 has been demonstrated to downregulate the expression of STAT3 in human cervical and colorectal cancer cells." (PMID 34530740, 2021). "Supporting this hypothesis, high STAT3 activity in CAFs correlates with poor patient prognosis in colorectal cancer and inactivation of STAT3 reduces tumor burden in a murine model of inflammation-associated colon cancer." (PMID 34858425, 2021). "However, more detailed molecular mechanisms, such as the genomic and proteomic responses underlying the EGCG-induced colorectal-cancer-cell apoptosis, how EGCG suppresses STAT3 promoters, anti-metastasis, and anti-angiogenesis, remain to be elucidated." (PMID 33747527, 2021). "A study confirmed that STAT3 is essential for proliferation and survival in colon cancer-initiating cells, and the IL-6/STAT3 pathway regulated the proliferation and contributed to the survival in colorectal cancer." (PMID 34165442, 2021). "OLA1P2 could block phosphorylated STAT3 homodimer formation and activate the STAT3 signaling pathway, inhibiting colorectal cancer cell growth and metastasis." (PMID 34926688, 2021). "Reportedly, IL-6 secreted by colorectal cancer-derived MSCs could activate JAK2/STAT3 signaling and promote the progression of colorectal cancer." (PMID 34789315, 2021). "STAT3 is the intracellular signal gate keeper of a variety of cell surface receptors with inflammatory activity and is involved in numerous disease entities, including colorectal cancer." (PMID 33530306, 2021). "Besides canonical HH signaling, GLI was activated by AKT and signal transducer and activator of transcription 3 (STAT3) in colorectal cancers." (PMID 34440799, 2021). "In another colorectal cancer study, piperine inhibited the migration and invasion of cancer cells, reversed the epithelial-to-mesenchymal transition biomarker expression, and downregulated STAT3 expression." (PMID 33921897, 2021). "In addition, lncRNA ITIH4-AS1 forms a complex with FUS and STAT3, and helped STAT3 nuclear translocation to activate JAK/STAT3 signaling, exerting pro-tumor functions in colorectal cancer." (PMID 35096622, 2021). "To determine whether PRKAR2A regulates STAT3 activation through IL-6, we transiently transfected human colorectal cancer cell line RKO with specific PRKAR2A small interfering RNA (siRNA) or control siRNA, and a clear knockdown of PRKAR2A was achieved." (PMID 34349238, 2021). "Further, in contrast to normal colorectal tissues, STAT3 acetylation was highly elevated in colorectal tumor tissues, as shown by fluorescent IHC staining of human colorectal tumor tissue array and 1 colorectal cancer (CRC) patient-derived xenograft (PDX) tumor tissue (respectively)." (PMID 33491667, 2021). "Furthermore, nifuroxazide was reported to inhibit the STAT3 signaling, which enhances antitumor immunity and reduces colorectal cancer metastasis." (PMID 34833950, 2021). "Laminin α5β2γ1 enhances colorectal cancer cell self-renewal through STAT3 activation." (PMID 35008625, 2021). "Besides, EGCG downregulated significantly STAT3 and p-STAT3 expression in these three colorectal-cancer cell lines." (PMID 33747527, 2021). "Indeed, in colorectal cancer, the activation of STAT3 following irradiation allowed the cells to be intrinsically radioresistant through the activation of Cyclin D2 (CCND2) transcription." (PMID 34141616, 2021). "Previous reports suggest that KDM4B silencing inhibits the activity of STAT3 signaling in colorectal cancer, and thus, we tried to detect whether KDM4B can regulate the activity of STAT3 signaling in RA FLS." (PMID 33909202, 2021). "LncRNA BCAR4 maintains colorectal cancer cell stemness by targeting the miR-665/STAT3 pathway." (PMID 34349799, 2021).
colorectal cancer (continued). "IL-6 is one of the abundantly expressed cytokines in the colorectal cancer microenvironment through gp130 activation on tumor cells with subsequent signaling through Janus kinases (JAKs) and signal transducers and activation of transcription 3 (STAT3)." (PMID 32422984, 2020). "In this study, we found that WCAF can downregulate the expression of STAT3 and p-STAT3 proteins in xenografts of HCT-116 in nude mice, inhibit the STAT3 signaling pathway in colorectal cancer, and effectively inhibit tumor growth in combination with the anti-angiogenic agent BEV." (PMID 33746736, 2020). "The miR-125b–STAT3 axis has a reported involvement in tumor cell proliferation, apoptosis and migration, for example, in osteosarcoma cells, liver, lung and colorectal cancer cells, melanoma cells, laryngeal and oral squamous cell carcinoma cells, and cervical cancer cells." (PMID 32161621, 2020). "Regorafenib could increase signal transducer and activator of transcription 3 (STAT3) phosphorylation in colorectal cancer cells, HCT116 and HT29." (PMID 33023006, 2020). "Lipopolysaccharide facilitates PKM2 binding to the STAT3 promoter, subsequently promoting STAT3 transcription and its nuclear translocation and inducing pro-inflammatory cytokine secretion and cell proliferation in colorectal cancer." (PMID 33292198, 2020). "Furthermore, in colorectal cancer Mir34a was shown to constrain carcinogenesis by directly inhibiting an IL-6R/STAT3/Mir34a feedback loop, and its ablation is required to induce IL6-mediated EMT and invasion." (PMID 32541781, 2020). "Our finding indicates that PT inhibited Bcl2 and BclxL protein expression in various colorectal cancer cells indicating that PT may alter NFkB and STAT3 pathway." (PMID 32703189, 2020). "ETBF infection induces chronic colitis, which is characterized by rapid and robust colonic activation of the signal transducer and activator of transcription 3 (STAT3) protein, which subsequently results in a T-helper type 17 (Th17) immune response and leads to the evolution of colorectal cancer." (PMID 32013191, 2020). "Moreover, IL-6-dependent activation of STAT3 was found to directly repress the miR-34a gene in colorectal cancer cells." (PMID 33371368, 2020). "The IL6/JAK/STAT3 pathway was reported to promote the metastasis of colorectal cancer." (PMID 32850443, 2020). "Studies have also shown that WCAF can inhibit the growth and liver metastasis of human colorectal cancer in nude mice, suppress tumor angiogenesis, and downregulate phosphorylation of signal transducer and activator of transcription 3 (STAT3) in gastric cancer cells." (PMID 33746736, 2020). "Moreover, a recent proteomic study reported the enrichment of GSTP1 and p-STAT3 in EVs from 5-fluorouracil-resistant colorectal cancer cells and the role of p-STAT3 in the transfer of resistance was further confirmed in vivo." (PMID 32384712, 2020). "Furthermore, Cer and PA attenuated expression levels of IL-10 in colorectal cancer cells co-cultured with M2 macrophages and downregulated STAT3 and NF-κB expression." (PMID 32222879, 2020). "Up-regulation of S1PR1 and STAT3 expression was shown to correlate with poor survival of colorectal cancer patients, which additionally advocates targeting S1PR1 to attenuate malicious feed-forward amplification loop involving S1PR1/STAT3 signaling as a strategy to combat colon cancer." (PMID 32456134, 2020). "Overall, STAT3/5 targeting siRNA is proven to promote apoptosis, cell cycle arrest, and suppress cancer cell invasion in various carcinoma cell-line models, including prostate, esophageal, hepatocellular, ovarian, laryngeal, breast, and colorectal cancer." (PMID 30847297, 2019). "Additionally, Gujral and colleagues 33 showed that FZD2 drives the EMT and cell migration in colorectal cancer by activating the Fyn and STAT3 signaling pathways." (PMID 31595151, 2019).